EP300 (EP300 lysine acetyltransferase)
Diseases named in the same sentence as EP300 in open-access papers (continued):
Sharing a sentence is not in itself a finding about the gene and the disease.
cancer (continued). "HDAC1 was shown to be one of the oncogenes deleted in the 1p deletion event, and SIRT2 and EP300 were two cancer suppressors lost in 19q deletion and 22q deletion events, respectively." (PMID 33718432, 2021). "The pathways highly enriched in EP300-wild-type pan-cancer were mainly involved in the stromal signature and metabolic process." (PMID 34616736, 2021). "In agreement with findings that EP300 increases migratory potential and invasiveness of cancer cells, we demonstrated reduced lung colonization and distant metastasis as well as circulating tumor cells via EP300 KD in TNBC cells." (PMID 33167919, 2020). "Recent studies have confirmed that deletion of EP300 in Tregs suppressed the proliferation and function of Tregs and limited the ability of cancers to avoid immune destruction, thereby decreasing tumor growth." (PMID 32012118, 2020). "CTCF, EP300 and LMO2 are listed in the Catalog Of Somatic Mutations In Cancer (COSMIC) as genes that are causally implicated in cancer if mutated." (PMID 32850701, 2020). "Others, such as FN1, EP300, CASP8, EGF and MAP2K1, which were associated with the pathways involved in cancer, were also hub-node genes." (PMID 31501464, 2019). "Enrichment of similar factors was found for cancer and aging, for example, EP300, FOS, and JUN, among others." (PMID 29504244, 2018). "Our data shows that inhibition of CREBBP/EP300 bromodomains can interfere with oncogene-driven transcriptional programs in cancer cells and consequently hold therapeutic potential." (PMID 29884215, 2018). "The targets of EP300 are enriched in normal cells rather than cancer cells in two GO terms, corresponding to apoptotic process and programmed cell death respectively, indicating the function of EP300 is altered in cancer cells." (PMID 30598101, 2018). "For example, EP300 plays an important role in regulating cell growth and blocking the promotion of cancerous tumors." (PMID 30598101, 2018). "Strikingly, both sample sets shared six genes in their ‘top 20’ list of most frequently lost ‘Cancer census genes’ (i.e. EP300, SETD2, PBRM1, CHEK2, MKL1 and MAPK1)." (PMID 29371938, 2017). "Compared with the upregulated genes following lncRNA625 knockdown, downregulated genes displayed higher statistical significance scores for EP300 occupancy in cancer cell lines (hypergeometric test)." (PMID 28194033, 2017). "EP300, in both sample sets the ‘Cancer census gene’ with the highest reported frequency of copy number loss, encodes an histone acetyltransferase, important in cell proliferation and differentiation." (PMID 29371938, 2017). "As in the TCGA-data, EP300 was the ‘Cancer census gene’ with the highest reported frequency of copy number loss, being in 71% of studied MPMs." (PMID 29371938, 2017). "Expression of cancer stem cell markers, as well as tumour sphere formation, was also increased in EP300-depleted cells, and was diminished in EP300-overexpressing cells." (PMID 28341962, 2017). "While in CESC and KIRC, both of these two cancer types had their own high‐frequency mutations, such as MLL3, EP300, and VHL." (PMID 26992457, 2016). "These included several cancer-associated genes such as MKL1, EP300, NF2, and HIC2 and chromatin binding genes BRD1, HIRA, and HDAC10." (PMID 25909290, 2015). "Third, mutations in chromatin regulatory factors such as SETD2, ARID1, SMARCA4, KDM6A, EP300 and MLL are emerging in various cancer types but, so far, only a few have been linked to altered methylome patterns." (PMID 25473433, 2014). "EP300 was found in the translocated cancer gene, transcription factor and tumour suppressor gene families." (PMID 24885312, 2014). "As a comparison, only five known cancer genes that are mutated in >10 cancer types (NF1, EP300, BRCA2, MLL, ARID1A) are longer than 4,450 bp." (PMID 23718799, 2013).
cancer (continued). "Luciferase reporter assays demonstrated that miR-574-3p directly binds to the 3′ UTR of several target genes (such as RAC1, EGFR and EP300) that are components of ‘Pathways in cancer’." (PMID 23554959, 2013). "Importantly, the majority of cancer cells are similarly sensitive to targeting EP300/CBP proteins through chemical inhibition of either the histone acetyltransferase or bromodomains of these proteins." (PMID 38664416, 2024). "Furthermore, ASCC exhibited somatic missense mutations in cancer driver genes, with KMT2C, PIK3CA, and EP300 being the most mutated genes, in agreement with previous reports." (PMID 39024554, 2024). "Previous study reported that the deletion of EP300 promoted the cancer stem cell differentiation." (PMID 38693103, 2024). "In addition to direct inhibition of CREBBP/EP300, blocking the interaction of CREBBP/EP300 with other oncogenic molecules is also an important anti-cancer pathway." (PMID 36831561, 2023). "Although mutated EP300 failed to convert the overall survival at pan-cancer level, high transcriptional activities in EP300:H3K27ac (rather than EP300:H3K4me1) target genes resulted in a worse prognosis." (PMID 37876590, 2023). "Acute catalytic CREBBP/EP300 inhibition modulates transcription independently of DNA accessibility and selectively suppresses transcription of distinct oncogenic networks in different cancer types." (PMID 36831561, 2023). "Conversely, EP300 mutation did not affect the prognosis of overall survival at both pan-cancer level and cancer specific level." (PMID 37876590, 2023). "In addition to the clinical non-CREBBP/EP300 inhibitors (tucidinostat and PRI-724), two targeted inhibitors of CREBBP/EP300 are currently in clinical trials in cancer patients." (PMID 36831561, 2023). "Notably, seven genes associated across more than one cancer type, of which three (BRCA1, EP300, MTOR) associated with the same somatic mutational component across two different cancer types." (PMID 35764656, 2022). "Similarly in 2D coculture, inhibiting EP300 either pharmacologically or genetically in CAFs inhibited collagen deposition and reduced cancer cell and CAF proliferation." (PMID 35760868, 2022). "Hence, EP300 activity regulates collagen production in CAFs and can be targeted to reduce cancer cell growth." (PMID 35760868, 2022). "In addition, complementary to the reported synthetic lethality of targeting p300 in CREBBP-mutant cancer cells, the synthetic lethality of targeting CBP in EP300-mutant cases offers a potential alternative therapeutic opportunity for these patients." (PMID 35536676, 2022). "Despite these previous studies, a systematic investigation into the associations of EP300 mutations with genome instability and antitumor immunity in pan-cancer remains lacking." (PMID 34616736, 2021). "Many functions of EP300 may vary in cancers depending on the context, cellular identity, and perhaps environmental condition." (PMID 34149798, 2021). "Nevertheless, a systematic investigation into the associations of EP300 mutations with genome instability and antitumor immunity in pan-cancer remains lacking." (PMID 34616736, 2021). "EP300 (CEA level ≥ 5: 20.8%, CEA level < 5: 9.2%; p = 0.048) is a histone acetyltransferase, where its role in cell proliferation and differentiation can be associated with cancer." (PMID 35003350, 2021). "Remarkably, cancers with EP300/CBP LOF showed higher neoantigen amount, supporting the notion that tumor immunoediting shapes the neoantigen landscape and that EP300/CBP may be part of this process." (PMID 33602823, 2021). "EP300 is described as oncogene in triple negative BC regulating cancer stem cell." (PMID 33670375, 2021).
cancer (continued). "Finally, a heterozygous germline EP300 mutation results in reduced p300 abundance that manifests as Rubinstein–Taybi syndrome (RSTS), a condition characterized by increased cancer predisposition." (PMID 34452526, 2021). "Despite the cancer-promoting effects of EP300, multiple lines of evidence suggest that EP300 may also be involved in cancer suppression." (PMID 34149798, 2021). "Furthermore, we found that EP300-mutated cancers showed significantly higher programmed death-ligand 1 (PD-L1) expression levels than EP300-wild-type cancers in four cancer types, including BLCA, HNSC, UCEC, and STAD." (PMID 34616736, 2021). "Among the top 50 transcription factors and chromatin remodelers that appear at the promoters of genes overexpressed in cancer cells (Log2FC > 0.4), we identified enzymes EP300 and HDAC1, which we previously showed to create a functional unit with BRG1 at gene promoters in human macrophages." (PMID 32033115, 2020). "In cancer, CREBBP/EP300 is targeted by both mutations and structural alterations." (PMID 32493417, 2020). "Probes targeting EP300/CREBBP were designed as cancer therapeutics." (PMID 33575256, 2020). "Although EP300/CREBBP-inactivating mutations have been observed in some cancers, secondary gain-of-function mutations in EP300/CREBBP may further propel cancer development." (PMID 33117683, 2020). "In the unclassified subgroup, apart from previously reported mutations in epigenetic regulators in multiple cancers, including KMT2C, KMT2D, KMT2B, PRDM2, NCOR2, KAT6B, and EP300, in this cohort, we also found new recurrent mutations in epigenetic regulators, including CREBBP and PRDM16." (PMID 30950204, 2019). "Our results suggest that CREBBP/EP300 bromodomain inhibitors might be able to reduce the tumorigenesis of cancers governed by oncogenic transcription factors that depend on CREBBP/EP300 to stimulate transcription and therefore hold therapeutic potential." (PMID 29884215, 2018). "It has been reported that EP300 behaves as a classical tumor-suppressor gene in human cancers." (PMID 28938536, 2017). "Indeed, in addition to growth arrest, EP300 is involved in G1/S transition in human cancer cells and its inhibition can induce block of progression to the S-phase and apoptosis." (PMID 27903272, 2016). "Most of these genes have not been previously reported in SS, and neuroguidin (NGDN), RAS protein activator like 3 (RASAL3), KLHL34 and MUM1L1 have not previously been linked to cancer; only one gene (EP300) has been reported in SS." (PMID 26503545, 2015). "These genes include those mutated in other cancer types and bound with HCV proteins (e.g. PIK3R1 and EP300), genes interfacing with alternative partner groups (e.g. YWHAZ), and genes manifesting both differential co-expression and differential expression (e.g. ESR1)." (PMID 24564909, 2013). "However, despite extensive research on PRICKLE3, TNFSF10, ACSL1 and EP300 in relation to cancer, immunity, and metastasis, their precise involvement in primary resistance mechanisms in SCLC remains unclear and requires further study." (PMID 38957470, 2024). "Based on the known mechanisms of action of BET/EP300 inhibition in other cancers (i.e. MYC pathways inhibition) and that at least part of the UPS showed an enrichment of MYC targets, we hypothesized that targeting BET/EP300 proteins in UPS might be an interesting strategy." (PMID 39681067, 2024). "Consequently, the mutational status of CBP/EP300 may be leveraged as a biomarker for predicting the efficacy of small-molecule inhibitors of CARM1 in DLBCL and other cancers." (PMID 37536629, 2023). "Eight targets (EP300, CASP3, CASP8, CHEK2, CREBBP, NOTCH1, PPARG, and TGFBR2) were TSGs (gray text), suggesting that antagonizing these molecules might increase the susceptibility to cancer in healthy individuals." (PMID 37888486, 2023).
cancer (continued). "Recent cancer genome sequencing studies revealed mutations in many epigenetic modifiers that are associated with various cancers, such as DNMT3A in acute myeloid leukemia, IDH1/2 in glioblastoma, CREBBP/EP300 in small-cell lung cancer and ARID1A in gastric cancer." (PMID 35973998, 2022). "In addition, loss-of-function genetic mutations of the EP300 gene (encoding p300) and CREBBP (encoding CBP) in cancer suggest that CBP/p300 could serve as a tumor suppressor." (PMID 34201346, 2021). "Addition of glucose to gastrointestinal murine (STC-1) or human (HCT 116) cancer cells previously starved of glucose for 36 h leads to significantly increased cytoplasmic and nuclear EP300 levels as detected by western blotting and immunofluorescence; note that EP300 major fraction is nuclear." (PMID 32603375, 2020). "Abnormal activity of the bromodomains of CBP and EP300 may thus promote the onset of cancer." (PMID 26731516, 2016). "Genes related to cancer proliferation including NOTCH1 (p < 0.05), EP300 (n.s.), and PTCH1 (p < 0.05) were all upregulated in DR‐LSCC." (PMID 40385549, 2025). "The results revealed that the expression levels of EP300 and CREBBP (red bar) were greater in LAML than in other cancer types." (PMID 39885312, 2025). "Exploring selective inhibition and functional roles: Despite structural homology, EP300 and CBP exhibit distinct functional roles in gene regulation and cancer pathogenesis, concluding the need for the development of selective inhibitors." (PMID 41403952, 2025). "One study reported decreased H3K14ac enrichment due to reduced EP300 activity, accompanied by downregulation of TGFB in cancer cells." (PMID 41283357, 2025). "However, the mechanistic contribution of EP300 dysregulation to cancer is currently unknown." (PMID 41354653, 2025). "Expanding Targets Beyond EP300/CBP: Beyond EP300 and CBP, PCAF and GCN5 have emerged as context-dependent regulators in cancer, with inhibitors such as GSK4037 and L-Moses revealing their potential as therapeutic targets." (PMID 41403952, 2025). "Parallel suppression of SREBF2, mediated by decreased H3K27ac through EP300/CBP downregulation, undermines cancer cell metabolic plasticity." (PMID 41283357, 2025). "Recognizing this concern regarding toxicity, we sought to identify whether different cancers show enhanced susceptibility to bromodomain or HAT domain inhibition, for the purposes of nominating specific tumors for further exploration of specific types of EP300/CBP inhibitors." (PMID 38664416, 2024). "Here, we identify and separate the effects of targeting distinct domains of EP300 and CBP proteins across a panel of 460 cancer cell lines representing 31 distinct tumor types." (PMID 38664416, 2024). "Currently, the SE-related components recognized as cancer therapeutic targets are bromodomain containing 4 (BRD4), cyclin dependent kinase 7 (CDK7), E1A binding protein P300 (EP300), CDK8 and CDK19." (PMID 35303940, 2022). "EP300 and BAX contribute to the regulation of the cell cycle and apoptosis, cellular processes that are often impaired in cancer cells." (PMID 35664766, 2022). "Considering our current study, EP300 emerges as a key, chromatin-bound enzyme responsible for ABCC10 overexpression in cisplatin-resistant cancer cells of different tissue origin, e.g., lung and breast." (PMID 35205642, 2022). "We then confirmed the subcellular localization of EP300 and SMYD2 in cancer tissues using fluorescence co-localization experiments, and we found that SMYD2 had co-localization with EP300 in the nucleus in cancer tissues." (PMID 34544413, 2021). "It has been reported that MOZ/MORF is recurrently fused to EP300, CBP, or TIF2, resulting in mistargeted acetylation and enhanced cancer progression in leukemia." (PMID 34285329, 2021).
cancer (continued). "We found that LIHC and PRAD patients with gains in MHC-I AgPPM genes showed more frequent EP300/CBP LOF, suggesting a compensatory mechanism that allows cancers with elevated MHC-I AgPPM to evade immune recognition." (PMID 33602823, 2021). "To check if BRG1 creates a multi-enzyme complex with EP300 and HDAC1 in proliferating cancer cells, we searched for the latter two enzymes in BRG1 co-immunoprecipitates." (PMID 32033115, 2020). "By contrast, in healthy colon or other cancer cell types, glycogen storage blocks the ability of glucose to activate the reactive oxygen species (ROS)/AMPK/EP300/β-catenin axis." (PMID 32603375, 2020). "A recent study revealed that EP300‒BRG1 complexes, which were found in the promoters of DNA repair genes in macrophages, also operate in cancer cells and control the expression of the same group of functionally linked genes." (PMID 32900001, 2020). "Among these genes, PICALM (targeted by EP300), DDX6 (targeted by YY1) and LYL1 (targeted by LMO2) are reported on the COSMIC cancer gene list." (PMID 32850701, 2020). "For example, 90% sensitivity and 86% specificity for cancer detection was determined when methylation levels of the RASSF1 A, EP300 and CALCA genes were used in combination." (PMID 31450846, 2019). "Among eight HAMPs with M-scores > 0.4, EP300, PBRM1, and CREBBP had the largest overall M-scores across the 33 cancer types." (PMID 30760718, 2019). "Among the recurrent genomic events, those in BRD9, EP300, ATAD2, HDAC4, PRBM1, BRD4, and BRD1 were observed in the highest numbers of cancer types (nine, eight, eight, eight, seven, seven, and seven, respectively)." (PMID 30760718, 2019). "Our data show that inhibition of CREBBP/EP300 bromodomains can interfere with transcriptional outputs driven by oncogenes, such as GATA1 and MYC that function as transcription factors in cancer cells." (PMID 29884215, 2018). "Six other ‘Cancer census genes’ however, were listed among the most frequently lost ones, both in the TCGA- and LP-WGS-dataset (i.e. EP300, SETD2, PBRM1, CHEK2, MKL1 and MAPK1)." (PMID 29371938, 2017). "Our data reflect the heterogeneity of tumors in the H3/IDH1 wildtype group while also identifying two novel pHGG epigenetic cancer drivers (ZMYND11 and EP300) in this group." (PMID 29084603, 2017). "Specifically, three of the 17 cancer driver TFs were found to be over-represented (as predicted binding sites: BRCA1, CBFP and EP300; Fisher’s test p values < 0.05)." (PMID 27553366, 2016). "EP300, ISGF3G, STAT1, and STAT3 are up regulated in 8/13 of cancer models, while ATM, BAX, BCL2L11, HTATIP2, LGALS3, MAPK1, and TP73L are down regulated in half of cancer models." (PMID 19402918, 2009). "It is likely that dual inactivation of CREBBP and EP300 in tumors is critical and non-compensable, leading to high hypermutation in cancer genomes." (PMID 41301688, 2025). "Current drugs targeting EP300 are too broad and untargeted, lacking specificity to suppress a particular cancer-related function of EP300." (PMID 38256128, 2024).